BRCA2 (BRCA2 DNA repair associated)
Diseases named in the same sentence as BRCA2 in open-access papers (continued):
Sharing a sentence is not in itself a finding about the gene and the disease.
breast cancer (continued). "The lack of detection in BRCA2 led the authors to suggest that large rearrangements in BRCA2 might not play a role in inherited breast cancer in South African patients." (PMID 26577449, 2015). "However, the ER and PR expression of BRCA2-related breast cancers does not seem to differ from that of sporadic cancers." (PMID 26496879, 2015). "Previous studies by the Consortium of Investigators of Modifiers of BRCA1/2 (CIMBA) described the impact of 29 breast cancer susceptibility variants from non-hereditary breast cancer studies on ER-positive and ER-negative breast cancer risk in BRCA1 and BRCA2 carriers." (PMID 25919761, 2014). "This in turn may yield insights about the etiology of breast cancer in BRCA1 and BRCA2 carriers." (PMID 25919761, 2014). "Thus this study demonstrates that BRCA1 and BRCA2 large genomic rearrangements are unlikely to make a significant contribution to aetiology of breast cancer in Sri Lanka." (PMID 24906410, 2014). "Based on our data we cannot determine whether increased PMD in Ashkenazi Jewish women is associated with an increased risk of breast cancer independent of BRCA1 and BRCA2." (PMID 23668689, 2013). "Recently, three BRIP1 missense mutations have been identified in high-risk Jewish women, who have been tested negative for mutations in BRCA1 and BRCA2 genes, indicating that BRIP1 mutations can contribute to breast cancer susceptibility in Jewish high-risk families." (PMID 23586058, 2013). "A retrospective, multicenter cohort study was performed from 1996 to 2011 and comprised 6,235 women with unilateral breast cancer from 6,230 high risk families that had tested positive for BRCA1 (n = 1,154) or BRCA2 (n = 575) mutations or tested negative (n = 4,501)." (PMID 23216834, 2012). "Consequently, the poor uptake of existing breast cancer prevention options, which appears to be more marked in those with BRCA1 compared to BRCA2, serves to illustrate the urgent need to identify other agents for breast cancer prevention in this high-risk group." (PMID 26097796, 2012). "Likewise, the age at contralateral breast cancer was also significantly lower in the BRCA1 group than the BRCA2 group (P < 0.001) and the BRCA1/2 negative group (P < 0.001)." (PMID 23216834, 2012). "Although none of the families included in this study had male breast cancer cases, nine of them had a breast cancer/sarcoma phenotype; however, no BRCA2 rearrangements were identified, which may be related to the relatively small sample size." (PMID 22691290, 2012). "Younger age at first breast cancer was associated with a significantly higher risk of contralateral breast cancer in patients from BRCA1 positive and BRCA1/2 negative families and a trend was observed in patients from BRCA2 positive families." (PMID 23216834, 2012). "However, almost 70% of breast cancer families with four or more cases of early onset breast cancer under the age of 60 show no convincing evidence of linkage to BRCA1 or BRCA2." (PMID 22703186, 2012). "As compared to the presence of the variant allele among controls (17.3%), the increased frequency of the KRAS variant was confirmed in breast cancer cases from BRCA1 families (23.5%), but not among breast cancer cases from BRCA2 (13.5%) or non-BRCA1/2 families (15.8%)." (PMID 22436609, 2012). "In a Spanish study of 492 BRCA1- and BRCA2 tested-negative breast cancer patients with family history of breast and/or ovarian cancer, they identified 12 variants, of which one was clearly pathogenic in the subset of 106 cases with a family history of both breast and ovarian cancers." (PMID 21980511, 2011). "Therefore, hereditary but not sporadic breast cancer seems to be characterized by short telomeres, primarily in BRCA1 and BRCA2 mutation carriers, but also in a subgroup of BRCAX." (PMID 21829373, 2011).
breast cancer (continued). "Mothers and sisters of women with breast cancer diagnosed before the age of 35 years were at a substantially increased risk of breast cancer, by a factor that remained high even for those whose index cases had been tested and found not to carry mutations in BRCA1 and BRCA2." (PMID 20877337, 2010). "However, for most families who exhibit the characteristics of hereditary transmission of breast cancer, a BRCA1 or BRCA2 mutation is not detected." (PMID 19088722, 2009). "However, we estimate the lifetime risk for breast cancer to be 40% compared to 21% in the Collaborative Group study.However, in these studies, BRCA1 and BRCA2 testing were not conducted and mutation carriers were not excluded." (PMID 19088722, 2009). "This was compared with the observed numbers of 14 BRCA1, 11 BRCA2 and 25 total carriers (three BRCA2 carriers were among the 42 individuals excluded in the analysis because they had a single case of breast cancer and did not have any family history of cancer in the family)." (PMID 18627636, 2008). "Mutational analysis by direct sequencing of the entire coding region of the BRCA1 and BRCA2 genes on 37 breast cancer patients aged 40 years and under, with no reported family history of breast and/or ovarian cancers, identified a total of 14 BRCA1 and 17 BRCA2 sequence variants." (PMID 18431501, 2008). "It is not clear whether the prognosis for women with BRCA1 and BRCA2 related breast cancers differs compared to sporadic tumours with similar pathological prognostic indices." (PMID 17697367, 2007). "A high calculated risk from the Tyrer-Cuzick algorithms correlated closely with the subsequent occurrence of breast cancer in BRCA1 and BRCA2 mutation positive families, but this was less evident in families in which no pathogenic BRCA1 or BRCA2 mutation has been detected." (PMID 16507150, 2006). "However, for breast cancer the existence of known mutations that significantly increase risk (particularly mutations in the BRCA1 and BRCA2 genes, which are relatively common) rules out this solution." (PMID 17029623, 2006). "For this purpose, the complete sequence of the 47 exons and flanking intronic sequences of the ATR gene were analyzed in DNA samples from individuals affected with breast cancer from non-related BRCA1- and BRCA2-negative high-risk French Canadian breast/ovarian families." (PMID 17010193, 2006). "Multiple studies have found an elevated frequency of the 1100delC variant in specific stratifications of breast cancer patients with a family history of the disease, including BRCA1/BRCA2 negative families and families with a history of bilateral disease or male breast cancer." (PMID 15535844, 2004). "LOH at BRCA2 does not therefore appear to be a major prognostic marker in sporadic breast cancer." (PMID 9400936, 1997). "The prevalence of germline BRCA2, and seemingly lack of BRCA1, mutations (5%) among Brunei breast cancer patients is similar to that of other Asian populations further highlighting the difference in BRCA genetics and associated breast cancer risk in Caucasian and Asian populations." (PMID 40531958, 2025). "The possibility of developing breast cancer can be increased by various genetic or non-genetic factors, like the presence of mutations in breast cancer susceptibility one and two genes (BRCA1 and BRCA2), smoke, obesity, or prolonged exposure to estrogen and progesterone hormones." (PMID 40951838, 2025).
breast cancer (continued). "The prevalence of BRCA1 and BRCA2 pathogenic variants in breast and other related cancers in various populations and clinical management guidelines of affected individuals were well established, and similar data of non-BRCA breast cancer susceptibility genes were also increasingly published." (PMID 38355628, 2024). "Additionally, there may be a connection between the breast cancer-related tumor suppressor genes BRCA1/BRCA2 and RIBAS, although the exact mechanism is not yet fully understood." (PMID 39451649, 2024). "However, the development of breast cancer responds to multiple factors and not uniquely to the mitogenic activity of female hormones able to induce genomic instability that drives cancer development, as seen in BRCA1 and BRCA2 mutations." (PMID 38067328, 2023). "Therefore, further research is necessary to investigate whether or not the relationship between iNOS and BRCA2 in breast cancer cell lines follows the same trends as that of pancreatic and ovarian cancer cell lines." (PMID 35740092, 2022). "However, the exact rate of BRCA1/2 PV may be higher in patients with ER+/HER2- breast cancer, particularly because BRCA2 PV carriers frequently do not fully fill in personal or family testing criteria in approximately 50% of cases." (PMID 35158866, 2022). "Data from the U.S. suggest that mutations in the breast cancer susceptibility genes BRCA1 and BRCA2 may be more prevalent in African-American compared to non-Hispanic White women, while mutations in other breast cancer genes may be less common in African-Americans." (PMID 35012613, 2022). "Indeed, the estimated 20-year risks of developing contralateral breast cancer in this study were higher compared to a previously published study with a prospective design:1 47% versus 40% for BRCA1 heterozygotes and 40% versus 26% for BRCA2 heterozygotes, respectively." (PMID 34113011, 2021). "However, it is not clear whether germline mutations in other breast cancer susceptibility genes also predispose to TNBC, or whether the BRCA1 and BRCA2 genes interact and cooperate with other genetic susceptibility genes to drive TNBC." (PMID 30909550, 2019). "Furthermore, the G allele of rs1801123 was associated with an increased risk of breast cancer in women carrying the BRCA1 mutation, although in a recent study of the same group using a large set of BRCA1 and BRCA2 mutation carriers, its lack of association was revealed." (PMID 27483248, 2016). "Interestingly, there was a suggestion of an rs299290 association with ERα-negative breast cancer for BRCA2 mutation carriers, but in the opposite direction to that observed for BRCA1 mutation carriers: ERα-negative BRCA2 mutation carriers n = 434, per-allele HR = 0.83, 95% CI 0.70–0.97, p = 0.022." (PMID 25830658, 2015). "Finally, Signature 3 is associated with inactivating mutations in BRCA1 and BRCA2 genes, indicating that abrogation of functional HR- and/or NHEJ-mediated repair contributes considerably to breast cancer development, even in patients not harbouring a germline mutation in either of these two genes." (PMID 24792170, 2014). "To determine if SLX4 is involved in breast cancer susceptibility, we sequenced the entire SLX4 coding region in 738 (270 Jewish and 468 non-Jewish) breast cancer patients with 2 or more family members affected by breast cancer and no known BRCA1 or BRCA2 mutations." (PMID 23840564, 2013).
breast cancer (continued). "Because DSS1 maintains BRCA2 expression by regulating its ubiquitin-dependent degradation and because the BRCA1:BRCA2 imbalance promotes tumorigenesis by increasing genomic instability, we predicted that increased expression of DSS1 could suppress breast cancer development." (PMID 24289229, 2013). "On the other hand, tumours associated with BRCA2 mutations are of a luminal subtype, and tend to be of a positive oestrogen and progesterone receptors-status; negative HER-2, on the other hand, do not markedly differ from other hereditary or sporadic breast cancers." (PMID 20961453, 2010). "The present breast cancer risks represent the risks averaged over all possible polygenic and modifying effects and would therefore be applicable to a randomly chosen BRCA1 or BRCA2 mutation carrier (i.e., for a carrier without any knowledge of her family history)." (PMID 18349832, 2008). "Unlike breast cancer, where patients with germline mutations in BRCA1 or BRCA2 have cancers that are distinct from sporadic breast cancers on the basis of morphology or gene profiling, ovarian cancers with germline BRCA1 or BRCA2 mutations are indistinguishable from their sporadic counterparts." (PMID 18208621, 2008). "To investigate if variants of CHEK2 other than 1100delC confer an increased risk of breast cancer, we have screened a series of 68 familial breast cancer cases, which had been screened in the Regional Genetics Service and found to be negative for mutations in BRCA1 and BRCA2." (PMID 12454775, 2002). "At the pilot sites, PV/LPVs in breast cancer genes were most commonly identified in ATM, BRCA2, and BRCA1, whereas at the non-pilot sites, they were most commonly identified in BRCA2, BRCA1, and PALB2." (PMID 39292401, 2025). "Most of the patients did not have any second primary breast cancer (92.7%—BRCA-negative; 92.9%—BRCA1 group; 81.8%—BRCA2 group)." (PMID 41002733, 2025). "BARD1 carriers favor the development of high-grade invasion breast cancer, the same as BRCA1 carriers (p-value = 0.204), while BRCA2 carriers and non-carriers develops less aggressive tumors (p-values = 0.004 and <0.001 respectively)." (PMID 40805222, 2025). "Compared with HRDetect, CHORD requires less preprocessing of the data, was trained on a pan-cancer cohort as opposed to a breast cancer cohort, and includes the ability to predict BRCA1 vs BRCA2 subtypes." (PMID 39485057, 2024). "Given the patient’s family history of breast cancer, the patient was tested for BRCA1 and BRCA2 for which the results were negative." (PMID 38910622, 2024). "While BRCA1 and BRCA2 expression levels of breast cancer stem cells to which we applied the same dose increased in terms of DNA DSB repair, in the current study, it was observed that BRCA1 and BRCA2 levels decreased, but there was no significant change." (PMID 38367174, 2024). "Here we report on long-term breast cancer incidence and cumulative breast cancer mortality of a cohort of women with a BRCA1 or BRCA2 sequence variation who did or did not undergo MRI surveillance." (PMID 38421676, 2024). "Carriers were further categorised into those who had a FDR with breast cancer (FH+; n = 78 for BRCA1 and n = 170 for BRCA2) and those who did not (FH-; n = 152 for BRCA1 and n = 441 for BRCA2)." (PMID 37936660, 2023). "It has been demonstrated that some surgeons have performed bilateral breast mastectomies on patients with unilateral breast cancer with VUS in BRCA1 and BRCA2 without consulting a medical geneticist or a genetic counselor." (PMID 38028588, 2023).
breast cancer (continued). "The incidences of breast cancer in female relatives of BRCA1 carriers, BRCA2 carriers, and non-carriers were 33.0%, 32.2%, and 7.7%, respectively." (PMID 36861435, 2023). "Previous researchers detected only 24 mitochondrial variants predicted to be deleterious by SIFT and probably damaging by PolyPhen2 in a cohort of 436 French Nationals with familial breast cancer but testing negative for BRCA1 and BRCA2." (PMID 36758048, 2023). "In this study, we used the latest genetic sequencing technologies to investigate hereditary causes for the second breast cancer in individuals who are known not to have alterations in one of the three main breast cancer genes (BRCA1, BRCA2 and PALB2)." (PMID 36672364, 2023). "Among 4916 non-Jewish breast cancer cases undergoing full BRCA1 and BRCA2 testing, only two co-occurrences of BRCA1 and BRCA2 PVs has occurred including the single case reported in this study." (PMID 33758026, 2022). "BRCA2- related cancers, unlike BRCA1, frequently express estrogen and progesterone receptors and have many of the same features as sporadic breast cancer." (PMID 35409110, 2022). "For women aged 50 years or older at breast cancer diagnosis, RS often exceeded the chemotherapy benefit threshold (≥26) with BRCA1 (71.7% vs 14.4% with none; P <.001), PALB2 (37.1%; P = .001), and BRCA2 (44.3%; P < .001) PVs." (PMID 33426465, 2021). "Although the genomics features of mouse Brca1 mammary tumors have recently been analyzed by WES30,43, such analyses have not been reported for mouse Brca2 and Palb2 tumors." (PMID 33893322, 2021). "In this cohort study, 8396 patients with operable primary breast cancer (187 BRCA1 carriers, 304 BRCA2 carriers, and 7905 noncarriers) underwent BCT, mastectomy with radiotherapy, or mastectomy alone." (PMID 33890992, 2021). "In BRCA1 carriers, HRs of breast cancer after RRSO were not significant at 0.96 (95% CI, 0.73 to 1.26), nor were they significant in BRCA2 carriers (HR, 0.65; 95% CI, 0.37 to 1.16)." (PMID 34565426, 2021). "The fact that the control mice did not develop any mammary tumor while 50% or more of B1p53, P2p53, and B2p53 mice did clearly demonstrate the tumor-suppressive activities of BRCA1, PALB2, and BRCA2 in the mammary gland." (PMID 33893322, 2021). "Due to her personal and family history, positive for premenopausal breast cancer, the patient’s mother had previously undergone a comprehensive BRCA1/BRCA2 molecular analysis, which resulted negative." (PMID 32899294, 2020). "There were 133 deaths related to breast cancer: 101 non-carriers, 19 BRCA1 carriers, and 13 BRCA2 carriers." (PMID 32341426, 2020). "With regard to male breast cancer, routine screening is not recommended for BRCA1, while for BRCA2 annual clinical exam can be considered starting from age 40 onwards." (PMID 32655641, 2020). "These intervals correspond to, neither the previously identified Breast Cancer Cluster Regions (BCCR), nor the Ovarian Cancer Cluster Regions (OCCR) of BRCA1, and only marginally overlap with the BCCRs and the OCCRs of BRCA2." (PMID 30736435, 2019). "For women without breast cancer the mean age at BSO was 45.6 years (range 13–78 years), 44.7 years for BRCA1 carriers and 47.7 years for BRCA2 carriers." (PMID 30971774, 2019). "Thirty five out of three hundreds (12%) of BRCA1/2-sequencing negative familial breast cancer patients from non-Ashkenazi Jewish in US were found carrying BRCA LCRs, with 10% (31/300) LCRs detected in BRCA1 and 1% (4/300) detected in BRCA2, respectively." (PMID 31174498, 2019). "The difference regarding onset age of breast cancer between the BRCA1- and BRCA2-group was not statistically significant." (PMID 29176636, 2018).